PARP1 (poly(ADP-ribose) polymerase 1)
Diseases named in the same sentence as PARP1 in open-access papers (continued):
Sharing a sentence is not in itself a finding about the gene and the disease.
neurodegenerative disease (continued). "Herein, we summarized the relationship between different types of CNS diseases and PARP1, focusing on the roles of PARP1 in neurodegenerative diseases." (PMID 36438061, 2022). "PET imaging of PARP1 will significantly increase our understanding of the etiology and progression of neurodegenerative diseases and facilitate the discovery and development of novel CNS disease therapies." (PMID 36438061, 2022). "Neurodegenerative diseases are typical of the enhancement of PARP1 expression and the accumulation of PAR." (PMID 35806303, 2022). "In the last decade, a growing body of experimental evidence suggests that PARP-1 is activated in neurodegenerative diseases, neurodevelopmental disorders and aging, leading to neuroinflammation, autophagy dysregulation and mitochondrial dysfunction." (PMID 35455964, 2022). "This mode of PARP-1-mediated death has been observed in neurodegenerative diseases, and the expression of AMPA receptors has been confirmed in undifferentiated SH-SY5Y cells." (PMID 33562817, 2021). "In DNA damage-induced neurodegenerative diseases, PARP1 is hyperactive and leads to increased PAR levels, energetic breakdown, and cell death." (PMID 32327659, 2020). "The genetic or enzymatic modulation of PARP1 has been also proposed for other common neurodegenerative diseases, such as PD, ALS and AD." (PMID 30991935, 2019). "PARP-1 acts main role in DNA repair (Nazıroğlu, 2007) and its expression level is increased in neurodegenerative diseases such as SCI and SNI but it expression level was decreased in SNI and DRGN by antioxidants." (PMID 28620309, 2017). "Pharmacological inhibition or genetic deletion of PARP-1 is therapeutically effective in cardiovascular, inflammatory, vascular, and neurodegenerative diseases." (PMID 27027354, 2016). "In summary, our results suggest that PARP-1 inhibitor(s) and modulators of sphingosine-1-phosphate receptor(s) should be considered in potential therapeutic strategies directed at neurodegenerative diseases." (PMID 24420784, 2014). "Thus, most of the accumulating evidence linking PAR dysregulation with neurodegenerative disease points to increased PARP1 levels or activity, leading to increased PAR levels." (PMID 40905723, 2025). "In this context, developing new PARP1 inhibitors may be an excellent strategy to treat or prevent photoreceptor degeneration and other neurodegenerative diseases." (PMID 38397799, 2024). "In this regard, targeting PARP-1 is one of the most promising approaches for developing therapies that could delay the progression of AD and other neurodegenerative diseases." (PMID 39766263, 2024). "Notably, the overactivation of PARP-1 is observed in the lesions of neurodegenerative diseases, such as Parkinson's disease, Alzheimer's disease, and amyotrophic lateral sclerosis." (PMID 37060999, 2023). "Furthermore, enzymes other than SIRTs that use NAD as a co-factor are found to be alerted in neurodegenerative diseases such as poly (ADP-ribose) polymerase 1 (PARP1), and cyclic ADP ribose hydrolase (CD38)." (PMID 35875669, 2022). "In the next sections we will review the role of PARP-1 in examples of neurodegenerative diseases." (PMID 35158955, 2022). "Although miR-519a-3p and PARP1 move in opposite directions in terms of expression in the mentioned tumors compared to PDs, this does not mean that this model can be applied to all tumors or other neurodegenerative diseases." (PMID 35741059, 2022). "Therefore, some PARP-1 inhibitors were considered as drug candidates for neurodegenerative diseases such as AD." (PMID 34575823, 2021). "Moreover, excess PARP1 activation was demonstrated in aging and neurodegenerative diseases resulting mitochondrial dysfunction, neuroinflammation and dysregulation of autophagy (and mitophagy; e.g., via mTOR activation)." (PMID 34206738, 2021).
neurodegenerative disease (continued). "Hyperactivity of PARP-1 induced by changes in cell homeostasis promotes development of chronic pathological processes leading to cell death during various metabolic disorders, cardiovascular and neurodegenerative diseases." (PMID 34768872, 2021). "PARP-1 functions as a DNA repair enzyme but under intense DNA damage depletes the cell of NAD+ and ATP and leads to a non-apoptotic type of cell death called Parthanatos, which has been associated with the pathogenesis of neurodegenerative diseases." (PMID 32903806, 2020). "PARP1 is a key mediator of a distinct cell death pathway in several neurodegenerative diseases." (PMID 30974833, 2019). "In this way, the results of this study may advance the current knowledge of the mechanisms of biomolecular condensate formation involving a key DNA damage sensor, PARP1, and the RNA binding protein FUS, whose cellular functions are closely associated with neurodegenerative diseases." (PMID 39596510, 2024). "Moreover, we found an association of PARP1 activity with the formation and genesis/maturation of FUS-rich cytoplasmic inclusions, which are found in neurons of patients affected by certain major neurodegenerative diseases, including ALS." (PMID 36497190, 2022). "During intense oxidative DNA damage, hyperactivation of PARP1, results in NAD+ depletion which then leads to PARP–1–mediated necrotic death of cells, parthanatos, which has been implicated in various age–related neurodegenerative diseases and accelerated ageing." (PMID 34198948, 2021). "Although the immunomodulatory roles of PARPi are highly desirable in human malignancies, the ability for PARP1 degraders to prevent PARP1 trapping, and hence the activation of innate immune response could be useful in other contexts (e.g., ischemia-reperfusion injury and neurodegenerative diseases)." (PMID 32844745, 2020). "In neurodegenerative diseases, particularly Parkinson's disease, PJ34, a selective PARP1 inhibitor, has shown significant neuroprotective effects in experimental traumatic brain injury (TBI) by reducing neuronal death and microglial activation." (PMID 41460301, 2025). "This is also consistent with the concept that increased levels of PARP1 activity and PAR production, which is often observed in neurodegenerative diseases such as ALS, can generate large and often aberrant SGs." (PMID 41385186, 2025). "Numerous evidence also indicated that PARP1, SCD, AR, ALOX5, HIF1A are critical involved in HD or neurodegenerative diseases." (PMID 38918688, 2024). "More importantly, PARP1 activation promotes amyloid aggregation and toxicity, while PARP1 inhibition can significantly alleviate the disease symptoms in PD, as well as other neurodegenerative disease models, indicating that the downregulation of the response to DNA damage may be beneficial." (PMID 37047285, 2023). "Consequently, PARP1 inhibition can alleviate neuroinflammation, dysregulation of autophagy and mitochondrial dysfunction thereby inhibit development of inflammation(age)-related neurodegenerative diseases (or alleviate their symptoms), for example via SIRT1 activation." (PMID 34206738, 2021). "Overall, these studies support the idea that controlling PARP1 activity and SG behavior could be an effective strategy for treating ALS and other neurodegenerative diseases." (PMID 41385186, 2025). "Notably, activity of PARP1—an enzyme that produces ADPR -an endogenous activator of TRPM2 channels- is markedly upregulated in several neurodegenerative diseases, including PD and Alzheimer’s disease." (PMID 39117781, 2024). "The upregulation of PARP1 also leads to a drastic reduction of NAD+ levels, affecting ATP production and cell functions, which can lead to the development of other conditions such as diabetes, neurodegenerative diseases, and viral infections." (PMID 38258328, 2024).
neurodegenerative disease (continued). "Molecular interaction between PARPs and SIRTs and the role of PARP1 in neurodegenerative diseases is very complex and till now not fully elucidated." (PMID 28698968, 2018). "Moreover, PARP-1 also promotes the formation of TDP-43 and FUS-containing granules in the cytoplasm, two RNA-binding proteins that appear as neuronal cytoplasmic inclusions in neurodegenerative diseases such as ALS." (PMID 40931339, 2025). "Notably, and most importantly, cleaved PARP-1 was detected by stripping the PVDF membrane used for the detection of AdipoR1, so these results confirmed that AdipoR1 activation by Os-pep plays a key role in protection against neurodegenerative diseases." (PMID 33849621, 2021). "Repurposing of already approved PARP-1 inhibitors for pathological conditions characterized by PARP-1 hyperactivity could be an attractive strategy, since it may offer accelerated and cost-effective therapeutic opportunities for different neurodegenerative diseases, including AD." (PMID 35455964, 2022). "Although the study did not define PARP1’s function, PAR binding to hnRNPs caused the dissociation of hnRNPs from RNA, suggesting a reduction in hnRNP’s noncovalent bonds with PAR by a PARP inhibitor may improve treatments for neurodegenerative diseases." (PMID 31055645, 2019).
neurological diseases (34 papers, 2016 to 2026). "As PARP1 activation is a crucial mediator of neuronal death under excitatory toxicity, oxidative stress, ischemia, it is essential to understand the dynamic change of PARP1 in these neurological diseases and elucidate the pathogenic mechanisms." (PMID 36438061, 2022). "Multiple lines of evidence have shown that activated PARP1 is associated with intense DNA damage and irritating inflammatory responses, which are in turn related to etiologies of various neurological disorders." (PMID 36438061, 2022). "This post-translational modification known as PARylation results in changes in the activity of PARP1 and its substrate proteins and has been linked to the pathogenesis of various neurological diseases." (PMID 34708032, 2021). "In addition, excessive activation of PARP1 in microglia leads to glutamate uptake and neuronal injuries, which are associated with chronic neuroinflammation in neurological disorders." (PMID 40552150, 2025). "Intriguingly, the deletion and/or inhibition of PARP1 greatly reduces or prevents these pathologies in an Xrcc1-defective mouse model of SSB-associated neurological disease, highlighting excessive/aberrant PARP1 activity as a source of SSB-induced neuropathology." (PMID 34811483, 2021). "These neurological disorders have a common pathogenic mechanism, which is characterized by aggregation of cytotoxic proteins, elevated levels of oxidative stress followed by DNA damage, PARP1 activation and excess of cellular levels of PAR." (PMID 30991935, 2019). "In addition, we confirm that MCSZ is associated with hyperactivation of the single-strand break sensor protein protein poly (ADP-ribose) polymerase 1 (PARP1) following the induction of abortive topoisomerase I activity, a source of DNA strand breakage associated previously with neurologic disease." (PMID 31041400, 2019). "This also leads to the limitation of the use of PARP-1 inhibitors in treating nervous system diseases." (PMID 40017605, 2025). "Owing to its multivarious roles in cell death and energy metabolism, PARP-1 is involved in various neurological disorders including retinal pathologies." (PMID 39458649, 2024). "Owing to its promiscuous roles, poly (ADP-ribose) polymerase-1 (PARP-1) is involved in various neurological disorders including several retinal pathologies." (PMID 39458649, 2024). "Further investigation is warranted to elucidate the potential involvement of macroH2A in neurological disorders through its impact on PARP1." (PMID 39199381, 2024). "These questions need to be solved prior to translating PARP1 inhibition into therapies for MS and other neurological disorders and injuries." (PMID 34935305, 2022). "This concept provides rationales for preclinical studies exploring the neuroprotective role of PARP1 inhibition in various neurological disorders and injuries." (PMID 34935305, 2022). "Genetic defects in the repair of DNA single-strand breaks (SSBs) can result in neurological disease triggered by toxic activity of the single-strand-break sensor protein PARP1." (PMID 34811483, 2021). "Parthanatos, a new type of programmed cell death, resulting from poly (ADP-ribose) polymerase 1 (PARP-1) hyperactivation in response to DNA damage, was found to account for the pathogenesis of multiple neurological disorders." (PMID 33424554, 2020). "PARP-1 is a target for cleavage by caspase-3 (which also cleaves PARP-1 in neurological diseases) and caspase-7." (PMID 31313023, 2019). "Repurposing PARP inhibitors for non-oncological use could facilitate the development of novel therapeutic strategies, particularly in view of the apparent involvement of PARP1 in neurological disorders (NDs)." (PMID 40806211, 2025). "Moreover, activated caspase-3 cleaves PARP-1, suppressing DNA repair mechanisms and facilitating caspase-mediated DNA fragmentation, observed in various neurological diseases." (PMID 38674927, 2024).
neurological diseases (continued). "In particular, PARP1 plays a dualistic role in the cells of NS, acting on the one hand as a neuroprotector facilitating DNA repair and, on the other hand, inducing cell demise in various neurological disorders." (PMID 39767715, 2024). "Activated caspase-3 can also cleave PARP-1, which could suppress DNA repair and facilitate caspase-mediated DNA fragmentation; this phenomenon has been proven in several neurological diseases." (PMID 36771255, 2023). "Indeed, the chemical modulation of PARP1 can be proposed to ameliorate or treat many pathological conditions, from cardiovascular, inflammatory and autoimmune diseases to neurological disorders." (PMID 30991935, 2019). "Also, 59 unique proteins were associated with AD, and 10 of them (17%) showed an association with AD and an additional neurological disease (CTF1, NSF and PRSS53 with PD; SIGLEC9 with ALS; CR1, CTSH, PARP1 and PVR with MS; LRRC37A2 with both PD and ALS; and IDUA with PD, ALS and MS)." (PMID 40037332, 2025). "Paradoxically, PARP1 inhibition has potent cell death-inhibitory effects in other contexts, in particular against parthanatos, a non-apoptotic modality of cellular demise that relies on the enzymatic overactivation of PARP1 and that appears to be particularly prevalent in neurological diseases." (PMID 36743979, 2023). "Moreover, because the elevated PARP1 expression in response to oxidative/nitrosation stress has been found in many different neurological diseases, repurposing or developing novel PARP1 inhibitors as neurotherapeutic agents have piqued the interest of researchers." (PMID 36438061, 2022). "In turn, it activates the enzyme poly (ADP-ribose) polymerase-1 (PARP-1), which is also responsible for various neurological disorders." (PMID 38069355, 2023). "PARP1/2-directed noninvasive positron emission tomography (PET) has potential in diagnosing and prognosing neurological diseases." (PMID 36438061, 2022). "Importantly, inhibition and/or deletion of PARP1 or USP3 restores transcriptional recovery in XRCC1−/− cells, highlighting PARP1 and USP3 as possible therapeutic targets in neurological disease." (PMID 34811483, 2021). "In the other hand, the performed docking studies allowed explaining the PARP-1 inhibitory activity of perezone angelate, and ADMET studies showed its probability to permeate cell membranes and the blood–brain barrier, which is an essential characteristic of drugs to treat neurological diseases." (PMID 35268667, 2022). "Consequently, due to the dual role of PARP-1 in cellular processes, although PARP-1 inhibitors are currently employed in clinical settings for the treatment of tumors, the efficacy and safety of these drugs for neurological disorders require further investigation." (PMID 40017605, 2025). "However, there are no studies of macroH2A mediating neurological disorders through PARP1." (PMID 39199381, 2024). "Importantly, either PARP1 or USP3 inhibition/depletion rescue normal levels of histone monoubiquitination and transcription recovery following DNA base damage, highlighting these enzymes as possible therapeutic targets in the treatment of base excision repair (BER)-defective neurological disease." (PMID 34811483, 2021). "Thus, we hypothesize that PARP-1 may be altered in postmortem hippocampus of individuals with AD compared to age-matched controls without neurologic disease." (PMID 27034851, 2016).